CD4 (CD4 molecule)
Diseases named in the same sentence as CD4 in open-access papers (continued):
Sharing a sentence is not in itself a finding about the gene and the disease.
cancer (continued). "In cancer, the expression of TIM-3 on T lymphocytes may promote T cell exhaustion and the expansion of suppressive CD4+FoxP3+ regulatory T cells and CD11b+Gr-1+ myeloid-derived suppressor cells (MDSC)." (PMID 28674498, 2017). "The expression of PD-1 and Tim-3 on CD4+ and CD8+ T cells may also be a useful biomarker for predicting the efficacy of cancer immunotherapy." (PMID 28241889, 2017). "We also analyzed the percentage of lymphocyte subsets (CD4+, CD8+ and CD19+) expressing surface and/of intracellular CTLA-4 in cancer patients and healthy volunteers, aiming to figure out the correlation between lymphocytes CTLA4 locations and their susceptibility to cancers." (PMID 28211499, 2017). "The adaptive immune system has the capacity to elicit anti-cancer CD4+ and CD8+ T-cell responses, which are triggered by the presentation of cancer-derived antigens as human leukocyte antigen-binding peptides (HLAp) and their recognition by cognate T-cell receptors." (PMID 29104575, 2017). "(A) Pearson correlation R-values between the cell proportions predicted by EPIC and ISOpure and the observed proportions measured by flow cytometry or single-cell RNA-Seq, considering all cell types together (i.e., B, CAFs, CD4 T, CD8 T, endothelial, NK, macrophages and cancer cells)." (PMID 29130882, 2017). "Decreased percentages of naïve CD4+ T cells, naïve CD8+ T cells, CD4+ naïve/memory ratios, and CD4+CD45RA+CD45RO+ T cells and increased memory CD4+ T cells were observed in NSCLC patients, suggesting that the immune system was activated against cancer." (PMID 29137371, 2017). "At univariate analysis, the risk of cancer was associated with older age, not being on ART, low CD4 values, low CD4/CD8 ratio, high HIV-RNA values, low total cholesterol values, low HDL-c values, low LDL-c values, and high values of fasting glucose." (PMID 27603338, 2016). "CD4 cells are particularly involved in sending signals to other cells of the immune system, including the CD8 cells, which then destroy the infected (particularly the virus infected) cells and other damaged cells, including the cancer cells." (PMID 26934748, 2016). "As China’s national ART program began later than those of most developed countries and some HIV-infected patients were first identified at a late stage with low CD4 counts, it is reasonable that China still experiences HIV-related cancer epidemics in the ART era." (PMID 26883427, 2016). "Peripheral blood of NSCLC patients is characterized by a significantly higher percentage of Th17 (CD4+IL-17+) and Treg cells (CD4+CD25+FoxP3+) compared to individuals without cancer." (PMID 27784305, 2016). "Due to the low number of events, we were not able to search for an effect of the CD4/CD8 ratio on specific types of cancers." (PMID 27548257, 2016). "Stimulated production of Th1 effector cytokine IFN-γ by CD4+ T cells was not impacted by cancer while production of the Th2 effector IL-4 was significantly decreased in cancer septic mice." (PMID 27018973, 2016). "Similar to the pattern seen for CD4+ T-lymphocytes, CD68+ macrophages (TAMs) were observed predominantly in the superficial lamina propria of OLP and OLK tissues and/or the interstitial tissues of the cancer nests." (PMID 28053372, 2016). "Nevertheless, it is likely that anti-CTLA4 therapy plays a dual role by both removing pre-existing T regulatory cells and by blocking CTLA4-mediated suppression of CD4 and CD8 effector T cells; together permitting improved clearance of residual cancer cells following radiation therapy." (PMID 27281029, 2016). "This approach allowed the capture of CD4+ T-cells from the non-tolerized repertoire against foreign antigens, to enable induction of immunity against cancer targets." (PMID 27471642, 2016). "While cytotoxic T lymphocytes (CTL) (CD3+CD4-CD8+) could directly kill targeted cancer cells, helper T cells (CD3+CD4+CD8-) play important roles in the regulation of adaptive immunities." (PMID 27767031, 2016).
cancer (continued). "On the other hand, the infiltration of CD4+ or CD8+ lymphocytes in cancer tissues was not altered by the administration of ONA (data not shown)." (PMID 27404320, 2016). "Cancer septic mice had decreased number and frequency of splenic CD4+ lymphocytes secondary to increased apoptosis without changes in splenic CD8+ numbers." (PMID 27018973, 2016). "Recent clinical trial data on patients with B cell non-Hodgkin lymphoma and chronic lymphocytic leukemia demonstrated the high anti-cancer activity of CD19-CAR-T cells generated from a composition of CD8+ and CD4+ T cell subsets that were separately expanded in vitro and infused at a ratio of 1:1." (PMID 26999211, 2016). "The expression of TIGIT on cancer patients’ (n = 35) circulating CD8+ T cells (not circulating CD4+ T cells) was significantly lower than that of normal donors (n = 10)." (PMID 27577071, 2016). "Adaptive immune responses characteristically involve CD4+ T cells, CD8+ T cells and B cells, all of which may participate in spontaneous and induced responses to cancer in patients." (PMID 27121060, 2016). "In addition to impairing the activation of cytotoxic T lymphocytes (CTLs) and Th1 CD4+ cells, IL10 inhibits the cytolytic activity of natural killer cells and CTLs, which are responsible for the immune surveillance of cancer." (PMID 26956044, 2016). "In our study, patients with lethal non-AIDS-related cancers were moderately immunosuppressed (median CD4 cell count at 287 cells/mm3, despite an increasing proportion of patients with a HIV RNA <500 copies/ml (from 61% in 2005 to 89% in 2010)." (PMID 26083524, 2015). "In contrast, treatment with the known anticancer agent FR901228 induced Annexin V staining of all the cancer cells tested as well as activated CD4 T-cells, but not in naïve CD4 T-cells." (PMID 26734508, 2015). "Next, we investigated whether TR-CD4, through direct recognition of cancer cells, could enhance proliferation and survival of CD8+ T cells, which is one of the important functions of CD4+ T cells." (PMID 26447332, 2015). "Unfortunately, expansion of ART for individuals with low CD4 counts alone is unlikely to substantially reduce cancer burden in sub-Saharan Africa." (PMID 26267867, 2015). "At cancer diagnosis, patients with NADC were older than those with ADC (median age of 45 [IQR 39–53] vs. 39 [IQR 33–46] years, p <0.001) and showed a higher CD4 cell count (median of 334 [IQR 180–482] vs. 145 [IQR 46–329] cell/mm3, p <0.001) (data not shown in Table)." (PMID 25884678, 2015). "Therefore, we compared the frequency of CD4+ and CD8+ T cells and the CD4+/CD8+ ratio between the peripheral blood and the breast tissues and also between the cancer patients and the healthy controls using flow cytometry." (PMID 25605488, 2015). "Increased proportions of CD4+CD25+Treg cells have been observed in patients with different types of cancer; thus, how to eliminate the suppressive function of Treg cells is a key question in cancer immunotherapy." (PMID 25593198, 2015). "In contrast to CD4+ T cells, if CD8+ T cells were above 13, 5-year OS probability was around 90% and RFS rate was above 95% in cancer patients, whereas only 45% of OS and 50% of RFS in CD8+ T cells ≤13 cancer patients." (PMID 25968569, 2015). "Previous studies have indicated that PSP could significantly increase the percentage of CD4+ T lymphocytes, the ratio of CD4+/CD8+ and the quantity and percentage of the B lymphocytes and finally enhanced the immune system of cancer patients." (PMID 26032186, 2015). "Taken together, these data suggest that circulating LAP-positive CD4+ Foxp3+ Tregs, rather than the general population of CD4+Foxp3+ T cells, can be used as a more accurate and specific marker for monitoring the immunological status of cancer patients." (PMID 25268580, 2014). "Human purified CD4+CD25+ Treg cells isolated from PBMCs of control and cancer patients suppressed proliferation but did not mediate autologous CD4+CD25− responder cell apoptosis." (PMID 24475019, 2014).
cancer (continued). "The DP8α LPL lines and their CD4 counterparts were incubated with the bacteria alone or with a mix of allogeneic monocytes (as monocytes from the patients with cancer were usually not available) previously loaded overnight with each bacterium." (PMID 24714093, 2014). "Collectively, the data presented in this study suggest that a single peptide containing multiple SIM2 epitopes can be used to induce both a CD4 and CD8 T cell response, providing a peptide-based vaccine formulation for potential use in immunotherapy of various cancers." (PMID 24690990, 2014). "The lymphocyte subgroups CD3+, CD4+ and CD8+ and the CD4+/CD8+ T-cell ratio may be valuable indices for the prediction of the prognosis of patients with malignant tumors." (PMID 24649272, 2013). "CD4 counts at diagnosis were lower for KS cases (median: 69 cells/mm3; IQR: 34–227) and NHL cases (median: 153 cells/mm3; IQR: 89–263), but were more similar to the entire patient population for other cancer cases (median: 370 cells/mm3; IQR: 159–582)." (PMID 23705808, 2013). "Also, we have recently reported that a CD4+CD73+CD39(−) subset of T cells, most CD19+ B cells which are CD39+CD73+ and CD39+CD73+ exosomes isolated from the plasma of NC or cancer patients are all good ADO producers in the presence of exogenous ATP." (PMID 23898333, 2013). "The HIV viral load and CD4+ T cell counts were similar in both KS and non-KS malignancy groups (data not shown)." (PMID 23874201, 2013). "The majority of Tim-3+ CD4 T cells in the peritumoral stroma did not express Foxp3, whereas most Tim-3+ CD4 T cells in the cancer nest co-stained brightly with Foxp3." (PMID 23526963, 2013). "In contrast, the majority of Tim-3+ CD4 T cells isolated from the peripheral blood of healthy donors and cancer patients did not express the Treg-related molecules CD25 and Foxp3." (PMID 23526963, 2013). "Endogenous HER2-specific CD4+ T cells and antibodies have been detected in patients with HER2-expressing cancers, and in clinical trials, HER2-specific CD4+ and CD8+ T-cell responses could be induced by peptide vaccination." (PMID 23941509, 2013). "Because HHV-6 has low virulence and infects CD4+ T cells, macrophages, and dendritic cells, recombinant HHV-6 vectors have been expected to be useful in gene therapy of HIV infection and cancer." (PMID 23409116, 2013). "We analyzed helper T lymphocytes, cytotoxic T lymphocytes, and natural killer T cells, identified respectively by CD4, CD8 and CD56 markers in human normal colorectal mucosa, microadenomas and carcinomas, using immunofluorescence techniques and protein quantification analyses by Western blot." (PMID 23349906, 2013). "Importantly, TIM-3 expression on CD4+ T cells correlated with poor clinicopathological parameters of NSCLC such as nodal metastasis and advanced cancer stages." (PMID 22363469, 2012). "Consequently, there is a growing interest in designing vaccines that can activate both CD4+ and CD8+ T cells and thereby simultaneously elicit humoral and cellular cancer immunity." (PMID 23189185, 2012). "Thus, we inspected the gene expression levels of the examined genes (CD4, CD25, FOXP3, TGF-β, IFN-γ, IL-10, CTLA-4, PD-1, PD-L1, ARG1) in the CRC patients and confirmed they were all upregulated in the cancer patients." (PMID 22496728, 2012). "PD1 blockade, currently undergoing extensive clinical trials for a variety of cancers, is largely expected to restore CD8+ T-cell antitumor function but may as well benefit CD4+ effector T cells." (PMID 22400040, 2012). "Since MCPyV-specific CD8+ and CD4+ T cells are found in MCC patients, the research of LT-specific immunotherapy is a logical step in generating an effective treatment for virus-induced cancer." (PMID 23095249, 2012). "In murine models, depletion of CD4+CD25+ T cells significantly augments the efficacy of cancer vaccination, underscoring the role of these cells in suppressing the immune responses against cancer cells." (PMID 23029485, 2012).
cancer (continued). "Studies have demonstrated that vaccination may also lead to the expansionof CD4+CD25+ Tregs, which ultimately bluntsresponses to cancer vaccines." (PMID 22802961, 2012). "The involvement of another β-herpesvirus, the human cytomegalovirus (HCMV), has not yet been proven in human cancer, even though recent findings have suggested its potential role in the development of CD4+ large granular lymphocyte (LGL) lymphocytosis." (PMID 22110893, 2011). "Shortcomings of CD4 counts appear in certain clinical scenarios including identification of immunological nonresponders, subsequent development of cancer on antiretroviral treatment, failure on treatment simplification." (PMID 21679413, 2011). "In summary, the data presented herein show that CD4 T cell help is not required for functional, protective memory T cell responses to cancer." (PMID 22046294, 2011). "In contrast, IFN-γ-producing NY-ESO-1-specific CD4+ T cells were detectable after a single presensitization only in seropositive cancer patients but not in seronegative patients and healthy donors." (PMID 21858191, 2011). "Therefore, for the design of cancer vaccines, it is essential for activating robust and long-lasting CD4+ and CD8+ T cell responses in patients with cancer." (PMID 21048993, 2010). "Mean (SD) CD4 count was lower for ADC cases (176 cells/mm3: SD 195) compared with NADC cases and controls (non-infection-related cancers: 307 cells/mm3: SD 244; infection-related cancers: 257 cells/mm3: SD 211) and controls (309 cells/mm3: SD 242)." (PMID 21143940, 2010). "It is important to note that primary CD8+ T cell responses to nonmicrobial antigens, as in case of cancer, display an absolute dependence on CD4+ T cell help." (PMID 19812686, 2009). "The higher proportion of Foxp3+ cells in the SLN of the cancer patients was neither due to increased infiltration of CD3+ T-cells nor CD4+ T-cells." (PMID 19604349, 2009). "However, only DR-1-stimulated CD4 or CD3 T cells possessed cytotoxicity against peptide-pulsed autologous DCs and a cancer cell line, that expresses a high level of cyclin D1." (PMID 19707583, 2009). "Therefore, it is obvious that the balance of CD4+ T cell and CD8+ T cell is critical for prognosis of patients with cancer." (PMID 18349839, 2008). "This is in agreement with some reports, but not others, where CD4 responses have been found to be decreased in cancer." (PMID 15986031, 2005). "From an immunological perspective, these determinants may represent highly specific epitopes for T-cell (CD4+ and/or CD8+) recognition in cancer immunotherapy." (PMID 12592366, 2003). "High levels of CD4+ T cell, CD8+ T cell, NKC, and DC infiltration were recognised in 51.1% (23 out of 45), 37.8% (17 out of 45), 33.3% (15 out of 45), and 48.9% (22 out of 45) of cancer specimens, respectively." (PMID 14583778, 2003). "Therefore, current evidence does not indicate that baseline CD4+ T cell count is an absolute contraindication to ICI therapy in PLWH with cancer." (PMID 41924597, 2026). "This analysis suggested that 43% of the CD4 T cell‐related genes may not be specific to one cancer type, but we need more powerful GWAS data to validate the robustness of these marginal MR findings with weaker genetic signals." (PMID 41216857, 2025). "Compared with IL-2 as antitumor preparations in clinic, CD4+ T cell-derived EVs will not stimulate Tregs, which may suggest a promising new avenue for cancer immunotherapy by fostering a CD8+ T cell-mediated antitumor response." (PMID 40078996, 2025).
cancer (continued). "Among the various CD4+ T cell subtypes that regulate immune responses, the CD4+ T helper 1 (Th1) subset, which produces interferon (IFN)γ, tumor necrosis factor alpha (TNF-α), and interleukin-2 (IL-2), plays a central antitumor role by orchestrating cell-mediated immunity against cancer." (PMID 40543509, 2025). "After a kayaking ultramarathon, the CD4+/CD8+ ratio decreased, increasing further during the recovery period, which is not consistent with the starting value of our marathoner, which is similar (0.5) to some values observed for cancer patients in their worst recovery diagnosis." (PMID 41295784, 2025). "As a result, both spleen-selective LNPs-based mRNA vaccine formulations induced greater CD8+ and CD4+ T cell accumulation compared to PBS controls, indicating that the superior cancer immunotherapy efficacy may be attributed to the changes of microenvironment with enhanced immune cells infiltration." (PMID 41041043, 2025). "The observed increase in EV secretion from CD4 Tex cells in DLBCL, along with the characterization of various EV subpopulations, may provide a foundation for future studies investigating the role of TcEV in the pathogenesis of cancers." (PMID 40036846, 2025). "However, the focus of IGSF10 is not on its prospective correlation with the immunological system, for example, B cells, CD4+/CD8+ T cells, neutrophils, macrophages, and dendritic cells, but on the close implications in some developmental diseases and various cancers." (PMID 41447338, 2025). "In most cancer types, SF3B6 displayed a positive relationship with CD4+ Th2 T cells and common lymphoid progenitors, while demonstrating a negative correlation with various other immune and stromal cells.CD4+ Th2 T cells are a major subclass of helper CD4+ T cells." (PMID 40356980, 2025). "In addition, various immune cells in the TIME, such as CD4 memory T cells, M2 macrophages and resting mast cells, were negatively correlated with Hub-EGFR.Sig in most types of cancer, while follicular helper T cells, active mast cells, eosinophils and plasma cells were positively correlated." (PMID 40574864, 2025). "Higher CD4 counts reduced rates of both fatal and non-fatal events after several cancers." (PMID 41463249, 2025). "In the context of cancer immunotherapy, although CD4 + T cells may not be as central as CD8 + T cells, they still hold significant value in the immune response against tumors." (PMID 41035074, 2025). "The LLC murine model of severe cancer cachexia demonstrated some of the most distinct differences in immune cell populations compared to TF mice and even compared to non-cachectic MC38 and mildly cachectic CMT-167 TB mice, such as decreases in CD8+ and CD4+ T cells and NKCs." (PMID 41479891, 2025). "Therefore, rGRA6Nt is a novel protein adjuvant that has an unique activity to selectively activate production of both IFN-γ and IL-18 by innate immune cells to potently activate cancer-specific CD8+ cytotoxic T cells and IFN-γ production by both CD4+ and CD8+ T cells." (PMID 40832663, 2025). "Furthermore, high GPX8 expression was found to be correlated with a higher degree of CD4+ T cell-infiltrating in COAD and neutrophil-infiltrating in STAD, indicating that GPX8 may play a role in immune evasion in cancer progression." (PMID 39833079, 2025). "Notably, CD4+ and CD8+ T cells are well-established for their potent antitumor activity, while dendritic cells and macrophages play critical immunomodulatory roles across multiple cancer types." (PMID 40766337, 2025). "On the other hand, isolated itolizumab-treated CD4+ T cells did not increase cancer cell lysis." (PMID 40391211, 2025). "However, we did not observe these effects in CD4+ T cells except for the reduction of Pd‐1 in cancer tissues from 4T1‐sh‐mR1#1 cells compared to that from 4T1‐sh‐Ctrl cells." (PMID 39932384, 2025).